CD28 (CD28 molecule)
Diseases named in the same sentence as CD28 in open-access papers (continued):
Sharing a sentence is not in itself a finding about the gene and the disease.
Myalgia (1 paper, 2022). "rs733618 of CTLA4 (additive, p<0.001; CT+TT vs. CC, p=0.011) and rs3181097 of CD28 (additive, p=0.016; GG+AA vs. AA, p=0.036) were associated with myalgia." (PMID 36389676, 2022).
myasthenia gravis (1 paper, 2020). Myasthenia gravis (MG) is a rare, clinically heterogeneous, autoimmune disorder of the neuromuscular junction characterized by fatigable weakness of voluntary muscles. "Eight associations (five variants) were not previously reported to our knowledge, including associations near IRF1/IL5 for myasthenia gravis, near TNFSF11 for RF− JIA, and near CD2/CD28 for EGPA." (PMID 33239102, 2020).
mycoplasmosis (1 paper, 2017). "The median IFN‐γ in supernatant of cultivated PBMCs that were stimulated with anti‐CD3 and anti‐CD28 antibodies in the cattle with mycoplasmosis was significantly lower than that in the healthy cattle (P < 0.01)." (PMID 28544524, 2017).
Myocardial fibrosis (1 paper, 2025). "CD28-based second-generation CARs, studied in myocardial fibrosis, offer high cytotoxicity and cytokine secretion but a limited lifespan." (PMID 40977952, 2025). "In the studies on myocardial fibrosis–related CAR-T cell therapy, the second-generation CAR with the CD28 costimulatory domain was used exclusively." (PMID 40977952, 2025).
myocarditis (1 paper, 2026). Myocarditis is a condition that is characterized by inflammation of the heart muscle (myocardium). "To facilitate the clinical translation of FAP.CAR-T cells in treatment of myocarditis, we constructed a CAR molecule targeting human FAP based on MO36 mAb clone by fusing its scFv fragment with human CD28 and CD3z endodomain (referred as hFAP.CAR)." (PMID 41356193, 2026).
myositis (1 paper, 2016). "As shown in the examples and in the summary graph, CD4+CD28null T cells were less sensitive towards glucocorticoid-mediated suppression compared to their CD28+ counterparts in myositis patients (median suppression: 46.8 % versus 68.5 %, n = 6)." (PMID 27039301, 2016).
nematode infections (1 paper, 2014). "To address these questions for nematode infections, we utilised CD28−/− mice, and more importantly a recently established conditional CD28 deleting mouse strain (CD28−/loxCre+/−), where CD28 deletion is induced by oral administration of the estrogen analogue tamoxifen." (PMID 24516382, 2014). "Some studies have suggested that CD28 costimulation is not required for recall of protective memory responses to nematode infections." (PMID 24516382, 2014).
nephritis (1 paper, 2022). Inflammation of renal tissue. "In addition, the proportion of CD4 + CD28− T cells in SLE patients with nephritis was significantly higher than that in those without nephritis (16.94 ± 2.562 vs. 4.687 ± 0.88, P = 0.012)." (PMID 36320075, 2022).
Nephroblastoma (1 paper, 2024). An embryonal neoplasm characterized by the presence of epithelial, mesenchymal, and blastema components. "Finally, the results showed that there were significant differences in CD80, CD48, IDO2, CD276, CD28, and CD200R1 between both groups, which could be used as potential therapeutic targets for the treatment of nephroblastoma." (PMID 38526609, 2024).
Nephropathy (1 paper, 2018). A nonspecific term referring to disease or damage of the kidneys. "CD28+γδT cell percentage in the kidney of mice with LPS nephropathy was significantly lower than that of control mice, indicating that CD28 in γδT cells had likely bound B7-1 on podocytes." (PMID 29862277, 2018). "CD28+γδT cells were decreased, indicating CD28 may play a role in LPS nephropathy." (PMID 29862277, 2018).
osteoarthritis (1 paper, 2022). A noninflammatory degenerative joint disease occurring chiefly in older persons, characterized by degeneration of the articular cartilage, hypertrophy of bone at the margins and changes in the synovial membrane. "In particular, we show that CD3/ICOS costimulation plays a major role in pathways related to STAT3 function and osteoarthritis (OA), whereas the CD3/CD28 axis mainly regulates p38 MAPK signaling." (PMID 36131938, 2022). "However, the highest scores were reached by the osteoarthritis (OA) pathway for ICOS and by the p38 MAPK pathway for CD28." (PMID 36131938, 2022).
osteomyelitis (1 paper, 2021). An acute or chronic inflammation of the bone and its structures due to infection with pyogenic bacteria. "During osteomyelitis, an increased number of CD4+CD28- T lymphocytes was observed in bone tissue, which was associated with long-term activated T cells, CD11b overexpression, and enhanced cytotoxic ability, all characteristics of T-cell senescence." (PMID 34341698, 2021).
pertussis (1 paper, 2024). A contagious bacterial respiratory infection caused by Bordetella pertussis. "Additionally, CD25 on transitional B cells and CD3 on CD28+ CD4+ T cells play important roles in protecting against pertussis." (PMID 39612418, 2024). "Our study results indicate that 11 types of immune cells have a protective effect against pertussis, with the strongest protection observed from CD25 on CD28+ CD4+ cells (OR = 0.3533, CI = 0.1636–0.7627, P = .008)." (PMID 39612418, 2024).
plasma cell dyscrasia (1 paper, 2019). "In vivo, CD8+CD28− T cells have been directly correlated with the suppression of antigen-specific T cell responses in patients with plasma cell dyscrasia." (PMID 31181772, 2019). "This immunosuppressive phenotype was initially observed in patients with plasma cell dyscrasia, where increased number of CD8+CD28− T cells was present in the bone marrow (i.e., TME) and the amount directly correlated with the suppression of antigen-specific T cell response." (PMID 31181772, 2019).
pleural mesothelioma (1 paper, 2018). A neoplasm that arises from the mesothelial cells of the pleura. "A significant fraction of both CD28 and 4-1BB mesothelin-specific CAR-T cells were found to co-express PD-1 and LAG-3 or PD-1 and TIM-3 in an orthotopic mouse model of pleural mesothelioma." (PMID 29364163, 2018).
progeria (1 paper, 2025). "Many genes, such as CCL2 and UCP2, were upregulated in progeria whilst CD27, CD28, and TIGIT were dysregulated in senescent cells." (PMID 40343591, 2025).
Q fever (1 paper, 2025). A bacterial infection caused by Coxiella burnetii. "It identified five hub genes (IL4, IL6, IL1B, CD28, and AKT1) that may contribute to the progression of Q fever by regulating immune responses." (PMID 41468478, 2025).
rectum adenocarcinoma (1 paper, 2019). An adenocarcinoma arising from the rectum. "High expression of CD28 and CD27 in HPV-positive HNSC and cytomegalovirus-positive colon and rectum adenocarcinoma tumors suggest an increase in the presence of CD28+CD27+ T-cells compared to virus-negative HNSC tumors and virus-negative colon and rectum adenocarcinoma tumors." (PMID 30911684, 2019).
renal carcinoma (1 paper, 2016). A carcinoma arising from the epithelium of the renal parenchyma or the renal pelvis. "Similarly to the effector T cell subsets, the frequencies of both CD4+CD25hiCD127lo and CD8+CD28-CD127loCD39hi Treg were significantly lower in the apparently unaffected renal tissue than in the autologous renal cancer tissue." (PMID 26824503, 2016). "The frequencies of four effector T cell subsets, namely CD4+IFNγ+, CD8+IFNγ+, CD4+IL17+, CD8+IL17+ T lymphocytes, and two Treg subsets, CD4+CD25hiCD127lo and CD8+CD28-CD127loCD39hi Treg, were comparatively analyzed in the peripheral blood of bladder and renal cancer patients." (PMID 26824503, 2016).
renal dysfunction (1 paper, 2022). "This association between day-15 solCTLA-4 and renal dysfunction might originate from the influence of Tregs on memory CD8+CD28− Teff, which has been recently implied in allograft dysfunction." (PMID 35109826, 2022).
Retinal atrophy (1 paper, 2020). A nonspecific term denoting wasting, especially as a result of degeneration, of the retinal pigment epithelium (RPE) and neurosensory retinal cells. "A key observation was that the levels of retinal atrophy were similar in mice receiving HEL-activated T cells or anti-CD3/CD28 activated T cells indicating that the atrophic changes in this model are not antigen-specific." (PMID 33013877, 2020).
retinoblastoma (1 paper, 2019). A malignant tumor that originates in the nuclear layer of the retina. "Further testing in preclinical mouse models will reveal whether there is a ranking between CD171- and GD2-specific CARs equipped with 4-1BB or CD28 costimulatory domains against retinoblastoma." (PMID 31500597, 2019).
rheumatic diseases (1 paper, 2018). "Unfortunately, mouse models on CD4+CD28− T-cells are not available so far, and therefore we have to rely on in vitro experiments as well as clinical studies to investigate the role of these cell subsets in rheumatic diseases." (PMID 29472917, 2018).
scoliosis (1 paper, 2025). A congenital or acquired spinal deformity characterized by lateral curvature of the spine. "BACH2 and HLA-G shared the same variant with CD28 on CD28+ CD45RA+ CD8+ T cell which could increase the risk of scoliosis." (PMID 40270514, 2025).
septic shock (1 paper, 2009). Shock caused by infection; frequently caused by gram negative bacteria, although some cases have been caused by other bacteria, viruses, fungi, and protozoa; characterized by fever, chills, tachycardia, tachypnea, and hypotension. "The number of circulating CD3+CD4+CD28+ T cells was significantly lower in surviving and nonsurviving patients with septic shock compared with healthy controls on admission and on day 3 of follow-up." (PMID 19243622, 2009).
serous carcinomas (1 paper, 2022). "Of the proteins assayed, only CD27 and CD28 showed statistically significant differences in median serum levels in patients with serous vs. non-serous carcinomas (p = 0.03, p = 0.04, respectively)." (PMID 35204342, 2022).
Shock (1 paper, 2009). The state in which profound and widespread reduction of effective tissue perfusion leads first to reversible, and then if prolonged, to irreversible cellular injury. "We found that a cutoff value of 136 CD3+CD8+CD28+ T cells/ml on admission to the ICU of a patient with septic shock showed a sensitivity of 70% and 100% specificity for predicting the risk of death, and the area under the ROC curve was 0.84." (PMID 19243622, 2009). "Our data indicate diminished circulating CD3+CD8+CD28+ T cell numbers in patients with septic shock with respect to healthy subjects on admission to the ICU and at least during the first 28 days of follow up." (PMID 19243622, 2009).
small bowel cancer (1 paper, 2016). "A meta-analysis of various population-based studies confirmed an increased risk for CRC and small bowel cancer in patients with CD28." (PMID 27087592, 2016).
Splenomegaly (1 paper, 2018). Abnormal increased size of the spleen. "TRPM7 kinase-dead (KD) K1646R knock-in mice exhibited splenomegaly and impaired blastogenic responses elicited by PMA/ionomycin or anti-CD3/CD28 antibodies." (PMID 29445164, 2018).
steatosis (1 paper, 2019). Increased lipid within the cytoplasm of cells. "Researchers have revealed that deletion of CD28 establishes a new pro/anti-inflammatory balance, and protects the liver against steatosis." (PMID 31269941, 2019).
thymic atrophy (1 paper, 2018). "Moreover, the circulating level of the proinflammatory cytokines IL-6 (associated with the decline in the efficacy of thymopoiesis) and TNF-α, which is shown to induce not only thymic atrophy, but also loss of CD28 expression on CD4+ T cells was investigated." (PMID 30086167, 2018).
ZIKV infection (1 paper, 2018). "The frequencies of Ki67+ central memory CD8+ (CD28+/CD95+/CD8+/CD3+) appeared to be higher in IVAG compared to sub Q ZIKV infection beyond 5 dpi (p = 0.03)." (PMID 30127237, 2018).
tumor (1,107 papers, 2003 to 2026). "CD28 expression is associated with immune cell infiltration in BC tumor microenvironment, particularly CD8+ T effector memory (Tem) cells." (PMID 41941486, 2026). "The proportions of CD8+CD28− and CD8+PD1+ T cells are associated with high-risk factors in EC, while tumor-infiltrating CD8+CD28+PD1− T cells independently predict relapse." (PMID 40136325, 2025). "In conclusion, our results suggest that targeted T-cell costimulation using bispecific antibodies that co-engage CD28 with a tumor-associated antigen has potential as a novel cancer immunotherapy." (PMID 39301613, 2025). "Tumor-infiltrating CD28+PD1−/CD8+ T cells were associated with tumor grade and LVSI, with multivariate analysis identifying low proportions as an independent predictor of relapse." (PMID 40136325, 2025). "By incorporating additional tumor-associated antigens or co-stimulatory domains (e.g., CD28, 4-1BB), TsAbs aim to enhance T-cell activation, broaden antigen coverage, and prolong immune responses." (PMID 40508128, 2025). "In recent years, researchers have achieved specific results in enhancing the anti-tumor function of CD28 by mutating its signaling motifs, combining the co-stimulatory structural domains, and modifying other CAR components besides co-stimulation." (PMID 40181986, 2025). "In summary, CD8+CD28− and CD8+PD1+ T cells are linked to high-risk clinical features in EC, while tumor-infiltrating CD8+CD28+PD1− T cells serve as a key independent prognostic marker for relapse." (PMID 40136325, 2025). "WES of purified, neoplastic T‐cell (CD3+PD1+) demonstrated high concordance with whole tumor biopsies and validated the presence of TET2 and DNMT3A in tumor and non‐lymphoid cells, but other mutations (CD28, RHOAG17V, IDH2R172, PLCG1) in neoplastic cells." (PMID 40510016, 2025). "We designed the bispecific antibody XmAb808 to co-engage the tumor-associated antigen B7-H3 with CD28 to promote T-cell costimulation within the tumor microenvironment." (PMID 39301613, 2025). "Further analysis categorized tumor-infiltrating CD8+ T cells into four subpopulations based on CD28 and PD1 expression, revealing associations with clinical characteristics." (PMID 40136325, 2025). "With tumor progression, the loss of CD28 expression in metastatic tissue indicates its involvement in metastatic mechanisms." (PMID 39684559, 2024). "Previous studies have shown that CD8 + CD28- T cell senescence is triggered by a variety of biological processes including telomere damage, Treg cells and tumor-associated stresses." (PMID 38459464, 2024). "Another possible explanation is that PD‐L1 binds two receptors, PD‐1 and B7.1 (CD80), and B7.1 is a key co‐stimulatory molecule on tumor‐associated dendritic cells (DC) that enhances T‐cell initiation through B7.1/CD28 interaction." (PMID 39500635, 2024). "Ablation of N-terminal ITAMS in CARs with CD28 costimulatory domain (XX3) had led to diminished anti-tumor efficacy, whereas CAR-T cells with C-terminal mutated tyrosine residues (1XX) outperformed the CARs without mutation." (PMID 38455066, 2024). "Collectively, we demonstrated that a high level of pTCD8+CD28- is associated with enhanced tumour immunity in HER2 + MBC." (PMID 38519706, 2024). "In the present study, we confirmed that high levels of circulating CD8+CD28+ T cells are associated with tumor response and prolonged PFS and OS." (PMID 38404585, 2024). "To further substantiate the association between pTCD8+CD28- and tumour immunity, we investigated the variations of pTCD8+CD28- mediated by immunotherapy." (PMID 38519706, 2024). "CD28-costimulation has been associated with rapid expansion and marked anti-tumor efficacy, and 4-1BB has been shown to enhance proliferation, to reduce exhaustion and to mediate long-term CART persistence." (PMID 37481608, 2023). "Based on initial reports, the idea was that the presence of 4-1BB/OX-40 would allow the CAR-T cells to persist longer, and CD28 would cause rapid tumor elimination." (PMID 37304291, 2023).
tumor (continued). "The anti-tumor effect of ICIs is associated with T-cell activation and CD28 expression; therefore, therapy is only effective against exhausted T cells and not against senescent T cells." (PMID 38136380, 2023). "Differently from CD28+ T cells, the increased PD1 levels in the tumor were associated with reduced functionality in PD1+CD28− T cells." (PMID 37898752, 2023). "Here, we describe CAR T cells targeting tumor-associated glycoprotein-72 (TAG72), utilizing the CD28 transmembrane domain upstream of the 4-1BB co-stimulatory domain as a driver of potent anti-tumor activity and IFNγ secretion." (PMID 37550294, 2023). "In some cases, poor responses to checkpoint blockade have been linked to suboptimal CD28 costimulation and the inability to generate and maintain a productive adaptive anti-tumor immune response." (PMID 35379805, 2022). "More specifically, CD28 augments the onset of early exhaustion which limits the associated anti-tumor efficacy and is in part responsible for their short-lived persistence in vivo." (PMID 36139142, 2022). "Defective cross-priming of CD8 T cells also caused protracted XBP1s upregulation, and CD28 downregulation combined with Foxp3 upregulation, evoking the phenotype of tumor-infiltrating CD8 Tregs in humans." (PMID 35237269, 2022). "CTLA-4 blockade contributed to the CD28-mediated proliferation of tumor-associated Tregs, inducing tumor immune tolerance ultimately." (PMID 36335094, 2022). "CK2 inhibitor can downregulate PD-L1 expression and enhance the level of CD80 on tumor-associated DCs and promote the CD80/CD28 interaction to enhance T-cell priming to inhibit tumor progression." (PMID 36530985, 2022). "Because also anti-CD3/CD28 stimulation led to lower responses upon coculture of these cell lines, the T-cell suppressive effect is likely caused by the tumor cells." (PMID 36875718, 2022). "Especially, inhibitory molecules TIGIT, CTLA4, and co-stimulatory molecules ICOS, CD28 whose expression was higher in tumor-associated Treg cells compared to that from normal tissues, were highly expressed in decidual Tregs." (PMID 34168655, 2021). "In BsAb therapy, while one antibody activates the effector T cell receptors such as CD3 and CD28, the other antibody causes a tumor-associated antigen, such as AFP, GPC3, and EpCAM, to initiate tumor cytotoxicity." (PMID 34696292, 2021). "The associated immune mechanism included reactivation of tumor–infiltrating T cells via CD28 costimulation by CD28 aptamer binding and crosslinking." (PMID 34532286, 2021). "This combination has shown to enhance CD8 T cell function in chronic viral infections and also has recovered tumour-infiltrating PD-1 unresponsive CD8 T cell due to loss of CD28." (PMID 33802622, 2021). "We next explored the causal relationship between CD73 and CD28 expressions on CD8+ T cells in tumor-bearing mice." (PMID 34011962, 2021). "Other bispecific aptamers have been engineered to specifically target CD28–expressing T cells in multidrug resistance–associated protein 1 melanoma that triggered prolonged survival of tumor–bearing mice." (PMID 34532286, 2021). "While the 4-1BB domain has been shown to improve persistence and expansion potential in CD8+ central memory T cells, CD28 was associated with more rapid tumour elimination, increased IL-2 secretion and preferential expansion of effector memory T cell subsets." (PMID 34638471, 2021). "Glycolysis is activated in rapidly proliferating tumor cells and immune cells including T cells and is associated with CD28 activation." (PMID 34149704, 2021). "The results showed that silencing of the expression of almost all autophagy-related genes decreased the susceptibility of the tumour cells to the apoptosis induced by CD3/CD28-activated human T lymphocytes." (PMID 32732922, 2020). "Cells expressing CD80 can induce cytotoxic T cell activation through association with CD28, a T cell costimulatory receptor, which promotes tumor clearance." (PMID 32514188, 2020).